CCL3 (C-C motif chemokine ligand 3)
Diseases named in the same sentence as CCL3 in open-access papers (continued):
Sharing a sentence is not in itself a finding about the gene and the disease.
multiple myeloma (continued). "Compared to the CD34+ cells from myeloma bone marrow, the expression of GATA1 in normal CD34+ slightly suppressed by the CCL3 treatment which also caused by pho-p38." (PMID 33239656, 2020). "In line with this, high levels of CCL3 was found in the bone marrow of patients with multiple myeloma, and anti-CCR1 and anti-CCR5 blocking antibodies inhibit the adherence of myeloma cells to bone marrow stroma cells in vitro." (PMID 32174921, 2020). "The Kaplan–Meier analysis based on the GEO data of individuals with NDMM (GSE2658) indicated that a high level of CCL3 significantly correlated with shorter overall survival in patients with myeloma (56.05 months vs. unreached, HR = 1.943, p = 0.0034)." (PMID 33239656, 2020). "Immunofluorescence staining indicated that CCL3 effectively activates p38 signalling with high levels of phosphorylated p38 in CD34+ cells derived from myeloma patients." (PMID 33239656, 2020). "Elevated CCL3 in the BM plasma of myeloma further inhibited the erythropoiesis of HSPCs via activation of CCL3/CCR1/p38 signalling and suppressed GATA1 expression." (PMID 33239656, 2020). "Our previous data indicated that the high level of CCL3 in the myeloma bone marrow microenvironment is probably involved in the myeloma-mediated inhibition of erythropoiesis." (PMID 33239656, 2020). "The MAPK signalling pathway, which includes ERK, p38 and JNK, is an important downstream modulator of CCL3 and plays a pivotal role in myeloma cell proliferation and myeloma-mediated bone disease." (PMID 33239656, 2020). "CCL3 is one of the major cytokines secreted by MM cells that promotes tumour cell proliferation and disrupts normal haematopoietic niches, thus inducing myeloma-related bone disease." (PMID 33239656, 2020). "Real-time PCR and Western blotting further indicated the recovery of GATA1 expression at both the mRNA and protein levels after blocking the CCL3/CCR1/phos-p38 signalling pathway in CD34+ cells from myeloma patients." (PMID 33239656, 2020). "Altogether, the data from our study showed that CCL3/CCR1/phos-p38 plays a pivotal role in erythropoiesis of myeloma HSPCs via downregulation of the transcription factor GATA1." (PMID 33239656, 2020). "CCL3 has also been shown to promote multiple myeloma cell migration and survival in the bone microenvironment." (PMID 31330786, 2019). "Another study also found osteoblast function was mediated by CCL3 in multiple myeloma in which multiple myeloma cells decreased osteoblast-induced decorin secretion." (PMID 31330786, 2019). "Excess CCL3 in the setting of myelogenous leukemias and multiple myeloma has been shown to inhibit osteoblastic activity and activate osteoclastic bone resorption leading to overall loss of bone." (PMID 30279500, 2018). "In particular, strong evidence exists regarding CCL-3 expression correlating with bone degeneration in patients with multiple myeloma providing proof regarding a link between CCL-3 activation and bone degradation." (PMID 30305140, 2018). "The agonistic effect of CCL3 on osteolytic lesions in patients with multiple myeloma is recognized; however, its role in skeletal damage during inflammatory arthritis has not been established." (PMID 30053130, 2018). "In hematologic malignancies CCL3 is a well-known mechanism of BMME disruption in multiple myeloma, both activating osteoclastic bone resorption, and inhibiting bone forming osteoblastic cells." (PMID 30279500, 2018). "Studies have shown that CCL-3 and CCL-4 are predominant factors responsible for the enhancement of bone resorption in multiple myeloma and play a causal role in the development of lytic bone lesions in vivo." (PMID 30305140, 2018). "Accordingly, CCL3 levels were increased in different types of tumours as hepatomas, multiple myeloma and chronic lymphocytic leukaemia." (PMID 28881626, 2017). "CCL3 enhances migration and signaling pathways mediating survival and proliferation in multiple myeloma cells." (PMID 28036258, 2017).
multiple myeloma (continued). "A few studies have demonstrated increased expression of CCL3 in human hepatomas, multiple myeloma and chronic lymphocytic leukaemia." (PMID 28881626, 2017). "Other chemokines have been shown to be elevated in patients with multiple myeloma including CCL3 and CCL20." (PMID 28389623, 2017). "Overexpression of CCL3 has been observed in B cell-related tumors, including multiple myeloma and chronic lymphocytic leukemia." (PMID 26713602, 2016). "We found that chemokines CCL3, CCL14, and CCL2 were highly expressed by myeloma and BM cells, and the levels of CCL14 and CCL3 in myeloma BM positively correlated with the percentage of BM-infiltrating MΦs." (PMID 26155942, 2015). "The increase in CCL3 levels contributes to the development of bone disease in multiple myeloma by supporting tumor growth and regulating osteoclast differentiation." (PMID 25893677, 2015). "For example, inhibition of HIF-1α in multiple myeloma cells was shown to decrease CCL3 secretion." (PMID 38273861, 2023). "In addition, in MM1.S cells, the protein levels of CCL3, a contributor to myeloma cell migration and an aggravator of bone disease, were decreased similarly in all conditions versus solvent." (PMID 37578563, 2023). "CCL3 was the main osteoclast-promoting factor in multiple myeloma, which was mediated by CCR1." (PMID 36468006, 2022). "Finally, myeloma cells construct a feedback loop to ensure their own growth by producing CCL3 (MIP-1α), and increase OC activity in combination with RANKL and MIP-1α in synergy with IL-6 to promote their survival." (PMID 33806209, 2021). "Targeting CCL3 would be a potential treatment strategy against bone disease and anaemia, which could essentially “kill two birds with one stone” in patients with multiple myeloma." (PMID 33239656, 2020). "Therefore, we investigated the effect of CCL3/phos-p38 activation on the erythropoiesis of HSPCs in the myeloma microenvironment." (PMID 33239656, 2020). "Thus, our study indicates that targeting CCL3 would be a potential strategy against anaemia and improve the survival of myeloma patients." (PMID 33239656, 2020). "Moreover, a previous study suggested that CCL3 reduces bone formation by inhibiting osteoblast function, including mineralization and osteocalcin production in myeloma-induced bone disease." (PMID 25893677, 2015). "Cytokines such as CCL3 has been found to inhibit osteogenesis in myeloma." (PMID 25260647, 2014). "Notably, CCL3 enhances osteoclastogenesis by signalling through CCR1 and CCR5 receptors and has been implicated in the osteolytic activity observed in pathological conditions such as multiple myeloma." (PMID 40471319, 2025). "Additionally, accumulating evidence indicates that ATM drives the BM-mediated resistance to chemotherapy in other hematological malignancies, such as multiple myeloma and acute lymphoblastic leukemia via upregulation of cytokines such as IL-6 or CCL3, CCL4, and GDF15." (PMID 36259537, 2022). "Therefore, our study strongly supports the rationale for the development of novel agents that simultaneously suppress myeloma cell growth and myeloma-related bone disease and compensate for normal haematopoiesis to prevent the activation of CCL3 and consequently improve myeloma-related anaemia." (PMID 33239656, 2020). "In addition, ERK pathway was also reported to be upstream of CCL3 in multiple myeloma cells." (PMID 32478376, 2020). "Importantly, blocking the CCL3 signal with BX471 (an antagonist of CCR1) effectively restored the effect of CCL3 on the downregulation of the transcription factor GATA1 in CD34+ cells in the myeloma microenvironment." (PMID 33239656, 2020). "In multiple myeloma (MM), OC exerts its effects by inhibiting MIP-1α/CCL3 signaling, thereby disrupting the adhesion of MM cells to stromal components and reducing IL-6 production." (PMID 40564985, 2025).
multiple myeloma (continued). "Patients diagnosed with conditions such as Sjögren’s syndrome, multiple myeloma, or rheumatoid arthritis often exhibit elevated levels of MIP-1α/CCL3." (PMID 40149646, 2025). "CCL3, in particular, is induced by RANKL during osteoclast differentiation and is a well-established factor that induces osteoclast formation in multiple myeloma." (PMID 29666038, 2018). "CCR5 receptor, that binds CCL3, CCL4, CCL5 and CCL8, is also involved in TAMs recruitment and plays a role in guiding invasion and metastasis of breast, cervical, lung, multiple myeloma, osteosarcoma, pancreatic, and prostate malignancies." (PMID 30591657, 2018). "First, the expression of CCR1 that binds to 6 ligands (CCL3, CCL4, CCL5, CCL7, CCL16, CCL23) has been shown to correlate with metastases in lung, prostate, cervical and hepatocellular carcinoma, multiple myeloma, T-cell leukaemia, and osteosarcoma." (PMID 30591657, 2018). "CCL3 and CCL4 expression has been detected in various B cell-related tumors, including multiple myeloma and chronic lymphocytic leukemia (CLL)." (PMID 28036258, 2017). "CCL3 and its receptors, CCR1 and CCR5, contribute to the development of bone disease in multiple myeloma by supporting tumor growth and regulating osteoclast differentiation." (PMID 26713602, 2016). "Other inflammatory cytokines known to support myeloma growth, such IL6 and CCL3 were also secreted into the supernatant after stimulation of the bone marrow monocytes with the TLR8 agonist." (PMID 26029369, 2015). "In summary, we characterized how CCL3 secreted by MM cells in an autocrine manner can drive M2 polarization and recruit CCR5 to the tumor area through paracrine signaling, thereby promoting myeloma progression and inducing drug resistance." (PMID 39953613, 2025). "Additionally, osteoclasts directly promote the survival and proliferation of myeloma cells by producing OPN,234 MIP-1a/CCL3, IL-6, Annexin II,198 BAFF240 and APRIL241." (PMID 36918531, 2023). "MIP-1α (CCL3) is a downstream target of FGFR3 and RAS-MAPK signaling in multiple myeloma." (PMID 34229750, 2021). "The chemokine cytokine ligand 3 (CCL3/MIP-1α) is a pro-inflammatory protein and chemokine mainly secreted by myeloma plasma cells and contributes to the development of myeloma-induced bone disease by supporting tumour growth and regulating osteoclast (OC) differentiation." (PMID 33239656, 2020). "Both CCL3 and CCL4 are also expressed in chronic myeloid leukemia and multiple myeloma." (PMID 33076281, 2020). "Interestingly, we found that a high level of CCL3 significantly suppressed GATA1 expression at both the mRNA and protein levels in CD34+ cells in myeloma bone marrow." (PMID 33239656, 2020). "Indeed, bone marrow levels of CCL3 and CCL20 have been shown to be higher in myeloma patients with increased levels of bone disease." (PMID 28389623, 2017).
Sepsis (58 papers, 2006 to 2025). Sepsis is defined as life-threatening organ dysfunction caused by a dysregulated host response to infection. "Specifically, we report here that CLP-sepsis caused a significant increase in IL-1β, IL-6, CCL3, CLL4, CXCL1, CXCL10 and GM-CSF, all of which contribute to sepsis-induced cytokine storm and, hence, to cardiac and organ dysfunction." (PMID 39559354, 2024). "Remarkably, the six sepsis-elevated genes in the lungs (Il10, Tnf, Ccl3, Ccl4, Ccl12, and Nos1) were more susceptible to the nuclear blockade with the NTCI than their homologs in the kidneys." (PMID 37638006, 2023). "In both neonatal mouse sepsis model and septic preterm infants, CCL3, CCL7, and CXCL10 were similarly up-regulated in blood and brain, promoting neutrophil migration across the BBB and exacerbating brain inflammation." (PMID 40254577, 2025). "Evaluation of the mouse sepsis model indicated that Abs-9 had a prophylactic protective effect against S. aureus infection and upregulating the levels of CCL3 and TNF-α." (PMID 39834865, 2025). "The results showed that the levels of Tnfα, IL-1β, CXCL2, CXCL10, CCL2, and CCL3 increased significantly in response to sepsis sEVs compared with healthy sEVs." (PMID 38910259, 2024). "The correlation matrices in the sepsis group produced a single cluster showing a positive interaction among the pro-inflammatory mediators (CCL3, CCL4, IL1β, IL-6 and TNFα)." (PMID 35811678, 2022). "There was a clustering of CXCL8, TNFα, CCL4, CCL3, IL-1β and IL-6in the sepsis group indicating a chronic inflammatory response which seems to be mediated mostly by monocytes, whereas the febrile controls had no specific pattern." (PMID 35811678, 2022). "Compared to those of control mice, mRNA levels of the IL-6, IL-10, and CCL3 in peripheral blood mononuclear cells (PBMCs) of septic mice were significantly increased, all of which are known to be key markers of sepsis severity and mortality." (PMID 33182773, 2020). "CCL-3 or macrophage inflammatory protein-1α (MIP-1α) also mediates sepsis-induced ALI via promoting neutrophil infiltration, pulmonary vascular leakage, and early mortality." (PMID 32849610, 2020). "Elevated levels of CCL3 have been detected within the first 24 hours of sepsis, suggesting its unique role in innate immune function." (PMID 31375728, 2019). "For the chemokines, CCL2 and CCL3 levels were elevated in the middle sepsis phase (12 h), while CCL5, CXCL9, and CXCL10 levels were significantly increased in the late phase." (PMID 31354717, 2019). "In vivo, CCL3 KO mice or WT mice treated with anti-CCL3 monoclonal antibodies were more prone to sepsis, suggesting a significant protective role for CCL3." (PMID 26818951, 2016). "Indeed, we detected lower levels of CCL1, CXCL8 and CCL3 in plasma from heatstroke patients than in plasma from sepsis patients." (PMID 40084252, 2025). "The antibody treatment exerted anti-inflammatory effects via simultaneous inhibition of IL-6, CXCL8/IL-8, CCL3/MIP-1, TNF-α, and IFN-γ production, and had direct and considerable suppressive effects on excessive CCL and CXCL gene expression associated with sepsis immunopathogenesis." (PMID 38177528, 2024). "In addition, CCL3 and CCL4 are associated with microRNA involvement in sepsis-associated immune responses." (PMID 36225326, 2022). "As sepsis is a systemic intravascular infectious disease, during sepsis, the endothelial cells in the cerebrovascular blood vessels also produce various chemokines, such as CCL2, CCL3, CCL5, CXCL1, CXCL2, CX3CL1, and CXCL8." (PMID 38585633, 2024). "The LR pairs in the sepsis-induced ARDS group, including FASLG−FAS, OSM−IL6ST, and CCL3/4/5−CCR1, were different from pairs in the sepsis-only group." (PMID 35222683, 2022). "Anti-IL-17A antibodies downregulate CCL3, CXCL1, and IL-6 in cardiomyocytes of mice with sepsis induced by CLP, suggesting that IL-17A contributes to sepsis-induced cardiomyopathy." (PMID 32849528, 2020).
Sepsis (continued). "γδ T lymphocytes present in the lungs of CLP mice were likely to be originated from peripheral lymphoid organs and migrated towards CCL2, CCL3 and CCL5, which were highly produced in response to CLP-induced sepsis." (PMID 26037291, 2015). "Sepsis-induced ARDS patients displayed FASLG−FAS, which reportedly is related to increased protein permeability in the pulmonary alveoli, and CCL3/4/5−CCR1, which is related to the chemokines and proinflammatory cytokines that participate in and promote inflammatory responses related to macrophages." (PMID 35222683, 2022). "Gene ontology of these 23 common DEGs showed that apoptotic process (TRAF1, TNFRSF9, ADORA2A, ZBTB16), negative regulation of transcription (SAP30, TSC22D3, ETS2, ZBTB16), and inflammatory response (TNFRSF9, CCL3, ADORA2A) are the main biological processes affected by sepsis treatment." (PMID 30086151, 2018). "Furthermore, RGS1, CCL3, and SOCS1 were connected to sepsis in animal studies, while for CTSD increased expression levels were observed in mice with induced septic shock." (PMID 25814982, 2015). "The in vitro neutralization of CCL2, CCL3 and CCL5 by mAbs inhibited γδ T lymphocyte chemotaxis towards the respective chemokines and lung homogenates obtained from CLP mice, suggesting that these chemokines coordinate γδ T cell in vivo migration into the lungs during severe sepsis." (PMID 26037291, 2015).